MMP9 (matrix metallopeptidase 9)
Diseases named in the same sentence as MMP9 in open-access papers (continued):
Sharing a sentence is not in itself a finding about the gene and the disease.
renal cell carcinoma (46 papers, 2006 to 2026). "Both MMP-2 and MMP-9 are implicated in angiogenesis which is critical for highly vascularized malignancies such as renal cell carcinoma." (PMID 31200666, 2019). "Tissue MMP-9 levels in renal cell carcinoma samples are strongly associated with high nuclear grade and shortened survival." (PMID 19904265, 2009). "Lnc-216 and OSTM1-AS1 also upregulate MMP2 and MMP9 in retinal endothelial function and renal cell carcinoma respectively." (PMID 40457415, 2025). "In another study, it was revealed that silibinin prevents the advancement of renal cell carcinoma induced by EGFR signaling through the inhibition of the EGFR/MMP-9 pathway." (PMID 38504785, 2024). "CD44, MMP-2, and MMP-9 are new potential molecular prognostic markers in renal cell carcinoma (RCC)." (PMID 36831550, 2023). "CD44 and MMP9 are frequently utilized as immunohistochemical markers that are concurrently evaluated in renal cell carcinoma (RCC) and have been identified as potential molecular prognostic markers for RCC." (PMID 37509716, 2023). "Overexpression of miR-133b significantly inhibits cell proliferation, migration, and invasion by targeting MMP9 in renal cell carcinoma." (PMID 35187068, 2021). "Research on its mechanism showed that miR-133b exerts this role via modulating the expression of MMP9 and inhibiting the progression of renal cell carcinoma." (PMID 35187068, 2021). "The presented results strongly indicate the potential significance of the Tu M2-PK, CA9, and MMP9 proteins as markers capable of predicting the disease course in patients with renal cell carcinoma." (PMID 34513052, 2020). "The results indicate a potential significance of Tu M2-PK, CA9, and MMP9 as biological markers for predicting the disease course in patients with renal cell carcinoma." (PMID 34513052, 2020). "TNF-α induced EMT in renal cell carcinoma by suppressing E-cadherin expression and promoting Vimentin and MMP-9 protein expression." (PMID 31068208, 2019). "Serum levels and tissue expression of MMP-9 are higher in renal cell carcinoma as compared with healthy controls." (PMID 19904265, 2009). "The aim of the study was to assess the possibility of using plasma levels of tumor M2-pyruvate kinase (Tu M2-PK), matrix carbonic anhydrase IX (CA9), and matrix metalloproteinase 9 (MMP9) in patients with renal cell cancer as predictors of the disease course and the response to treatment." (PMID 34513052, 2020). "We have previously demonstrated that RUNX3 decreased the activity of MMP-9 in renal cell carcinoma." (PMID 24475196, 2014). "Furthermore, MMP-9 expression by immunohistochemistry has been found to be significantly correlated with poor prognosis in renal cell carcinoma." (PMID 23281640, 2013). "In our study, mean MMP-2 and MMP-9 mRNA expression in the renal cell carcinomas was significantly higher than in the normal renal tissue (P <0.05), the levels of MMP-2 and MMP-9 mRNA expression were not correlated with tumor type or pathologic grade of renal cell carcinoma." (PMID 23281640, 2013). "We focus on the specific role of MMP2, MMP7, and MMP9 in clear cell renal cell carcinoma (ccRCC) and major subtypes of RCC." (PMID 41893368, 2026). "In renal cell carcinomas (RCC), TNF-α induced EMT of RCC cells by repressing E-cadherin, promoting invasiveness and activating MMP9 activity." (PMID 27429011, 2016). "TNF-α has also been shown to induce EMT and promote renal cell carcinoma (RCC) tumorigenesis and invasiveness by suppressing E-cadherin, upregulating vimentin, and increasing MMP9 expression." (PMID 39003350, 2024). "For example, FBXO22 reduces tumour metastasis via the suppression of matrix metalloproteinase‐9 (MMP‐9)‐involved invasion and migration and the blockade of VEGF‐induced angiogenesis in renal cell carcinoma." (PMID 39153212, 2024).
renal cell carcinoma (continued). "The ATP‐P2X6R can regulate the p‐extracellular signal‐regulated kinase 1/2 (p‐ERK1/2) /matrix metalloproteinase 9 (MMP9) signaling pathway, thereby promoting the migration and invasion of renal cell carcinoma cells." (PMID 37692109, 2023). "A recent study of renal cell carcinoma cells also demonstrated that POSTN overexpression increased the activity of MMP-2 and MMP-9." (PMID 35163164, 2022). "FBXO22 blocked metastasis via suppression of MMP9-mediated migratory and invasive ability and VEGF-involved angiogenesis in human renal cell carcinoma (RCC)." (PMID 36127346, 2022). "For example, as a member of the serum amyloid A family of apolipoproteins, SAA1 can increase the invasive capacity of tumor cells in RCC by inducing MMP-9 expression, which make it serve as a biomarker for the diagnosis and prognosis of advanced and metastatic renal cell carcinoma." (PMID 34712244, 2021). "In renal cell carcinoma, FBXO22 restrained cancer metastasis and progression by suppressing VEGF-induced angiogenesis and MMP-9-induced invasion and migration." (PMID 35046938, 2021). "In patients with renal cell carcinoma, a statistically significant increase in the level of Tu M2-PK, CA9 and a statistically significant decrease in MMP9 in comparison with the control group were found." (PMID 34513052, 2020). "The study about human renal cell carcinoma showed that elevated PDGF-D induced angiogenesis and metastasis in a mouse model, in which the expression of angiopoietin-1 and MMP9 were increased." (PMID 24646915, 2014). "In the present study, mean MMP-2, MMP-9, MT1-MMP, TIMP-1, and TIMP-2 mRNA expression in the renal cell carcinomas was significantly higher than in the normal renal tissue (P <0.05)." (PMID 23281640, 2013). "In summary, mean MMP-2, MMP-9, MT1-MMP, TIMP-1, and TIMP-2 mRNA expression in the renal cell carcinomas was significantly higher than in the normal renal tissue (P <0.05)." (PMID 23281640, 2013). "Mean MMP-2, MMP-9, MT1-MMP, TIMP-1, and TIMP-2 mRNA expression in the renal cell carcinomas was significantly higher than in the normal renal tissue." (PMID 23281640, 2013). "Mean MMP-2, MMP-9, MT1-MMP, TIMP-1, and TIMP-2 mRNA expression in the renal cell carcinomas was significantly higher than in the normal renal tissue (P <0.05)." (PMID 23281640, 2013). "In terms of tumor stage of renal cell carcinoma, the differences in MMP-2, MMP-9 and MT1-MMP mRNA expression levels were significant." (PMID 23281640, 2013). "In this study, we examined the expression of MMP-2, MMP-9, membrane-type 1 (MT1)-MMP, TIMP-1, and TIMP-2 in renal tissue samples of renal cell cancer and examined the correlation between their expression and clinicopathological parameters." (PMID 23281640, 2013). "Adiponectin, via AdipoR1, inhibits mTOR through AMPK activation in renal cell carcinoma (RCC), suppresses vascular endothelial growth factor (VEGF), MMP-2 and MMP-9 and increases TIMP-1 and TIMP-2 secretion, resulting in decreased growth, dissemination and angiogenesis of RCC." (PMID 37686525, 2023). "Depletion of CAPN2 could inhibit the expression of N-cadherin, vimentin and MMP9, and overexpression of CAPN2 could enhance N-cadherin, vimentin and MMP9 protein levels in renal cell carcinoma." (PMID 35707527, 2022). "A similar METTL14 expression pattern was found in renal cell carcinoma, and METTL14 further suppressed P2RX6 activation regulated metastasis of renal cell carcinoma via ATP‐induced Ca2+ influx modulating ERK1/2 phosphorylation and MMP9 signalling." (PMID 32808488, 2020). "Whether RSK4 can mediate the invasion and metastasis of renal cell carcinoma by CD44 and MMP-9 is a new direction proposed by this study." (PMID 32209138, 2020).
renal cell carcinoma (continued). "In the present study, we examined the expression of MMP-2, MMP-9, MT1-MMP, TIMP-1, and TIMP-2 mRNA in human renal cell carcinoma tissues by a reverse transcriptase-polymerase chain reaction (RT-PCR) assay and examined the correlation between their expression and clinicopathological parameters." (PMID 23281640, 2013). "Fisetin inhibited the migration as well as the invasion of human renal cell carcinoma (RCC) cells via the downregulation of CTSS and MMP-9 (ADAM9) and disintegrin." (PMID 36558146, 2022). "In contrast to other cancers such as renal cell carcinoma, we did not observe a correlation between JUNB, MMP2, and MMP9 expression, highlighting the dependency of JunB transcriptional programs on the tumor cell type." (PMID 34007044, 2021). "In terms of pathologic grade of renal cell carcinoma, the differences in MMP-2, MMP-9, MT1-MMP, TIMP-1, and TIMP-2 mRNA expression levels were not significant." (PMID 23281640, 2013).
renal carcinoma (45 papers, 2010 to 2025). A carcinoma arising from the epithelium of the renal parenchyma or the renal pelvis. "In addition, we observed a strong correlation of the SHN3 prognostic value with MMP9 and IL13Rα2 in highly aggressive brain tumors, thyroid and renal cancer, which supports a close functional association with these proteins." (PMID 37963919, 2023). "The aim of the study was to analyze whether the expression of CD44, MMP-2, and MMP-9 in association with the histopathological subtype of RCC affects the survival of patients with renal cancer." (PMID 36831550, 2023). "Hence, the aim of this study was to analyse whether the immunohistochemical expression of CD44, MMP-2, and MMP-9 in association with the histopathological subtype of RCC affects the survival of patients with renal cancer." (PMID 36831550, 2023). "Therefore, in this research, we answered the question of whether the immunohistochemical expression of CD44, MMP-2, and MMP-9 in association with the histopathological subtype of RCC affects the survival of patients with renal cancer." (PMID 36831550, 2023). "In Caki-1 and Achn renal carcinoma cells, melatonin inhibited MMP9 thorough a reduction of the NF-kB binding to the MMP9 promoter." (PMID 34209857, 2021). "TNF‐α induces EMT in renal cancer via repressing the E‐cadherin expression and enhancing Vimentin and MMP‐9 expressions." (PMID 33159487, 2020). "Specifically, NC reduced the level of phosphorylation of Akt and downregulated matrix metalloproteinase-2 (MMP-2) and MMP-9, leading to antimetastatic effects on renal cancer cells." (PMID 33288736, 2020). "They suggested 10 proteins for renal cancer exsome biomarker, 5 of which are abundant in renal cancer patients; matrix metalloproteinase 9 (MMP-9), ceruloplasmin (CP), podocalyxin (PODXL), dickkopf related protein 4 (DKK4) and carbonic anhydrase IX (CAIX)." (PMID 31686989, 2019). "It is well known that MMP-9 plays an important role in the invasion of cancer cells including renal carcinoma." (PMID 25849723, 2015). "Micro-vesicles shed by renal cancer stem cells contain pro-angiogenic factors, including gelatinase B/MMP-9, and promote the formation of a pre-metastatic niche, which is associated with unfavourable outcome." (PMID 24473089, 2014). "Ascochlorin was also reported to inhibit matrix metalloproteinase-9 (MMP-9) in human renal carcinoma (Caki-1) cells." (PMID 20335999, 2010). "Likewise, EGCG at concentrations of 20 μM or more was found to inhibit, by about half, the expression and activity of MMP-2 and MMP-9 in human renal carcinoma cells (786-0 and ACHN) and thus reduce their migratory and invasive potential." (PMID 39335164, 2024). "Moreover, PDGF-D enhances tumor metastasis and angiogenesis of renal cancer through increasing the expression of matrix metalloproteinase-9 (MMP9) and vascular endothelial growth factor (VEGF)." (PMID 28035069, 2017). "Furthermore, it has been shown that exosomes derived from renal cancer cells may contribute to renal cancer development, progression, and/or invasion via the increased expression of MMP-9." (PMID 36230852, 2022). "Research on renal carcinoma cells revealed that sunitinib not only decreased MMP-2 and MMP-9 activity but also suppressed the expression of EMT markers." (PMID 39968177, 2025). "A higher MMP-9 content and, on the other hand, lower specific activity in the cancer tissue suggest that MMP-9 is predominantly present in an inactive form in renal cancer." (PMID 38001735, 2023).
renal carcinoma (continued). "Cell cycle arrest can be induced by LGK974 by downregulating cyclin D1, c-Myc, MMP9, and MMP2 in renal cancer cells." (PMID 37763649, 2023). "In the case of renal cancer cells, P2X6 receptors were found to increase cell migration and invasion involving calcium-mediated p42/44 MAPK signaling and MMP-9 activation." (PMID 33584298, 2020). "We examined the expression of cytoplasmic β-catenin and Wnt target genes in renal cancer cells after treatment with LGK974, including the protein expression level of cyclin D1 and c-Myc and the RNA expression level of MMP9 and MMP2." (PMID 32104684, 2020). "It has been found that, in renal carcinoma cells, downregulation of MMP-9 leads to the decrease of VM formation, revealing that MMP-9 is necessary for VM formation in this cell type 6." (PMID 31772665, 2019). "The m6A-suppressed P2RX6 activation promotes renal cancer cells migration and invasion through ATP-induced Ca2+ influx modulating ERK1/2 phosphorylation and MMP9 signalling pathway." (PMID 31159832, 2019). "In particular, HIF-1α exclusively regulates glycolytic gene expression, whereas HIF-2α has been shown to promote tumor growth in a renal carcinoma xenograft model and invasiveness (through up-regulation of MMP-2, MMP-9, and PAI-1)." (PMID 31817100, 2019). "Also, resveratrol treatment (25 μM, 50 μM, 100 μM) limited the proliferation, migration, and invasion of neoplastic cells in renal cancer by inhibiting MMP-2 and MMP-9 and stimulating TIMP-1 by modulating the MAPK/ERK and PI3 K/Akt pathways." (PMID 39335164, 2024). "In addition to interfering with the activity of transcription factors, EF-24 was shown to resensitize renal cancer cells to TNF-related apoptosis-inducing ligand (TRAIL)-induced apoptosis via reducing intracellular ROS production and MMP-2/MMP-9 activity." (PMID 36900342, 2023). "MMP-9 showed a higher content than MMP-2 in both renal cancer grades, but we observed the enhanced activity of both gelatinases with an increase in the grade of renal cancer." (PMID 38001735, 2023). "A recent study reported that METTL14 could mediate P2RX6 mRNA and protein level, promoting renal cancer cells migration and invasion via ATP-induced Ca2+ influx modulating ERK1/2 phosphorylation and MMP9 signal pathway in vitro and in vivo assays." (PMID 32038982, 2020). "Furthermore, knockdown of Cul1 suppresses renal cancer cell migration and invasion abilities by up-regulating the expression of TIMP-1and inhibit the expression of MMP-9." (PMID 28108731, 2017). "Next, we found that in renal cancer cells, overexpression of MKRN2 led to elevated β-Catenin phosphorylation and reduced β-Catenin protein expression, resulting in the attenuation of Wnt pathway that is marked by the down-regulation of signature genes (c-Myc, Cyclin D, Axin2, Bcl-2, MMP2, and MMP9)." (PMID 40959281, 2025). "The correlation between MMP-9 and renal cancers has not been reported in previous studies." (PMID 35178444, 2022). "Moreover, the m6A-suppressed P2RX6 activation could promote renal cancer cells migration and invasion through ATP-induced Ca2 + influx modulating ERK1/2 phosphorylation and MMP9 signaling pathway." (PMID 33430867, 2021). "However, no studies of urinary MMP-9/NGAL complex in kidney carcinoma are currently available." (PMID 23760084, 2013).